LCN2 (lipocalin 2)
Diseases named in the same sentence as LCN2 in open-access papers (continued):
Sharing a sentence is not in itself a finding about the gene and the disease.
infection (continued). "Upon intoxication, infection, inflammation, and other forms of cellular stress, LCN2 is rapidly induced in injured hepatocytes." (PMID 34884961, 2021). "For example, an innate immune protein known to respond to bacterial infection, lipocalin-2 (Lcn2), shows robust induction following organoid infection." (PMID 34710062, 2021). "Based on the previously reported involvement of LCN2 in chemokine induction and in the recruitment of neutrophils at the sites of infection or tissue injury." (PMID 35111677, 2021). "In this case, IL-22 can significantly reduce infection by this pathogen via induction of other antimicrobial peptides such as lipocalin 2 (LCN2) and serum amyloid A1 and A2 (SAA1/2)." (PMID 33851257, 2021). "When LCN2 is missing, lowered resistance to infection results and the survival, virulence, and propagation of opportunistic, potentially life-threatening microbiota exploiting the siderophore-mediated iron uptake are favored." (PMID 34884961, 2021). "Our experiment confirmed that NF-kB can upregulate the expression of LCN2 and affect the polarization of M1 macrophages in the process of infection." (PMID 34616693, 2021). "An example is the ability of AMs to secrete the siderophore lipocalin-2 (LCN-2) during infection that binds to enterobactin-type and mycobacterial siderophores to sequester free iron." (PMID 33926483, 2021). "We observed more CD4+ T helper cells and CD8+ cytotoxic T cells in lungs of Lcn2-/- mice seven, nine and 16 days after infection." (PMID 33905460, 2021). "Lipocalin-2, also known as neutrophil gelatinase-associated lipocalin (NGAL), siderocalin, or 24p3, is a protein mainly secreted by neutrophils in response to infection and inflammation." (PMID 34917064, 2021). "In conclusion, our study underpins the notion that LCN2 is an important factor in innate immunity that prevents infections of bacterial pathogens by sequestering iron." (PMID 34884961, 2021). "We found that infection with Mtb H37Ra induced LCN2 production in bone marrow-derived dendritic cells (BMDCs)." (PMID 34563261, 2021). "Lipocalin-2 is as a pleiotropic molecule involved in a variety of physiological and pathological processes, such as metabolic homeostasis, apoptosis, infection, immune response, or inflammation." (PMID 34746212, 2021). "To further study the role of the microbiome, we co-housed WT and Lcn2-/- mice for 4 weeks prior to PR/8 infection to partially hybridize microbial profiles by passive transfer of microbiota." (PMID 33905460, 2021). "LCN2 secretion is induced by infection, damage, and metabolic disorders in various tissues and organs." (PMID 34359830, 2021). "We observed a significant increase in Lcn-2 levels, throughout the infection study, in mice fed control diet (from day 1 to day 3 post-infection)." (PMID 32737335, 2020). "To better characterize the inflammatory response induced during the course of infection, we quantified the micro-inflammatory marker lipocalin-2 (Lcn-2) in the stools, during infection." (PMID 32737335, 2020). "Lcn-2 level was 23.85 times lower in MS diet-fed mice compared to control diet-fed mice at day 3 post infection (p = 0.0159)." (PMID 32737335, 2020). "Acting as an anti-microbial acute phase reactant, the levels of lipocalin 2 (mouse Lcn2/human LCN2) are increased to limit the growth of pathogens upon infection." (PMID 32188494, 2020). "As macrophages produce the bacterial siderophore-binding protein Lcn2 to control infection, we also measured Lcn2 mRNA expression in spleens." (PMID 30723125, 2019). "While MNV-induced diarrheic responses were not affected, Stat1-/- mice additionally lacking either Nlrp3 or GSDMD displayed lower levels of the fecal inflammatory marker Lipocalin-2 as well as delayed lethality after gastrointestinal MNV infection." (PMID 31017981, 2019).
infection (continued). "In contrast, the induction of fecal Lcn-2 observed in MNV-infected Stat1-/- mice at three days post-infection was significantly diminished in both Stat1-/-Nlrp3-/- and Stat1-/-Gsdmd-/- mice." (PMID 31017981, 2019). "Lipocalin-2 (LCN2), also known as neutrophil gelatinase-associated lipocalin (NGAL), is an adipokine involved in a variety of processes such as metabolic homeostasis, apoptosis, infection, immune response, or inflammation." (PMID 31891637, 2019). "Similar to results observed with lipocalin-2, host lactoferrin is also involved in restricting iron; lactoferrin helped protect mice against infection by Mycobacterium tuberculosis and in some instances reduced granuloma severity." (PMID 30984629, 2019). "High concentrations of LCN2 in serum can be found in various diseases, especially in the case of inflammation developing, infection, or tissue ischemia." (PMID 31151292, 2019). "Specifically, the iron sequestration molecules haptoglobin and lipocalin-2 were >100-fold induced during infection." (PMID 31869388, 2019). "Lipocalin-2 (Lcn2), an innate immune protein, has come to be recognized for its roles in iron homeostasis, infection, and inflammation." (PMID 31375129, 2019). "After intragastric infection, the serum concentration of Lcn2 increased distinctly and then decreased fast." (PMID 31781104, 2019). "Lipocalin-2 (Lcn-2) protein is a component of the innate immune response whose expression has been shown to be upregulated during infection." (PMID 30936879, 2019). "Studies have demonstrated that LCN2 synthesis is increased systemically during inflammation and infection in several different human diseases." (PMID 31091692, 2019). "To test the role of Lcn2 in an acute lethal infection, we challenged Lcn2−/− or WT mice by intragastric administration with 2 × 108 CFU of E. coli O157:H7 and measured the bacterial burden." (PMID 31781104, 2019). "K. pneumoniae-infected mice demonstrated significantly higher Lcn-2 production as early as 4 weeks post-infection (p = 0.0051) that was sustained to 8 weeks (p = 0.0059)." (PMID 30833613, 2019). "Mono-infections in Lcn2+/+ mice also revealed a significant defect in growth of the KPPR1ΔgltA mutant." (PMID 31449551, 2019). "After intragastric infection, serum levels of Lcn2 increased to 1,110 ng/ml by 24 h, peaked at 3,270 ng/ml by 32 h, and then rapidly declined." (PMID 31781104, 2019). "In this study, we report for the first time that lipocalin-2 promote M.tb replication early in infection." (PMID 30534124, 2018). "At 3 weeks post-infection, expression of Lcn2 mRNA peaked in lungs and high amounts of lipocalin-2 were present in lungs and plasma." (PMID 30534124, 2018). "Feces were collected at different time points post-infection and used to evaluate inflammation by quantifying lcn-2 level and to analyze the gut microbiota composition by Illumina sequencing of the 16S rRNA gene." (PMID 30120269, 2018). "Here we show that lipocalin-2 surprisingly confers a growth advantage on M.tb in the early stages of infection (3 weeks post-challenge)." (PMID 30534124, 2018). "This fits a model where lipocalin-2 at the early stages of infection inadvertently feeds the macrophages with iron essential for mycobacterial growth thus giving the bacteria an initial growth advantage." (PMID 30534124, 2018). "This indicates that lipocalin-2 derived primarily from infiltrating neutrophils 3 weeks after infection promote the growth of M.tb." (PMID 30534124, 2018). "It has previously been reported that lipocalin-2 is important for control of M.tb during the chronic stage of infection." (PMID 30534124, 2018). "In a pneumonia infection model with Klebsiella pneumoniae, lipocalin-2 from both epithelium and neutrophils was equally important for full protection against infection." (PMID 30534124, 2018).
infection (continued). "Lipocalin-2 protein levels in the lung of WT/KO mice were significantly lower at all infection time points compared to uninfected WT controls, demonstrating that the baseline protein level must originate predominantly from circulating neutrophils." (PMID 30534124, 2018). "At 3 weeks post-infection the mycobacteria are primarily located within the lung parenchyma thus rendering the bacteria inaccessible for epithelia-secreted lipocalin-2." (PMID 30534124, 2018). "Iron is required for Plasmodium growth, and host iron-handling proteins can influence outcome of infection; for example, lipocalin-2, which can sequester iron, controls the severity of Plasmodium yoelii infection in mice." (PMID 28893916, 2017). "When combining mammary inoculation of LPS or LTA prior to a local S. aureus infection, we were able to modulate the innate immune response, reduce local bacterial loads, and induce either LCN2 or CHI3L1 at 24 h post-infection." (PMID 28791009, 2017). "Lcn2 is a chemoattractant for neutrophils, but this is unlikely to account for a survival difference beyond day 3 of infection." (PMID 28443246, 2017). "Lcn2 enhanced phagocytic bacterial clearance in macrophages in vitro after infection with Escherichia coli." (PMID 27734904, 2016). "At sites of infection LCN2 is secreted by neutrophils, macrophages, activated leukocytes, and adipocytes." (PMID 27729871, 2016). "This assumption was further confirmed in experiments showing that LCN2 has the capacity to limit bacterial growth by sequestering the iron-laden siderophore after infection in mice." (PMID 27729871, 2016). "Our data clearly demonstrated that Lcn2 enhances phagocytosis/autophagy pathways in macrophages after infection with E. coli." (PMID 27734904, 2016). "Lipocalin (Lcn2) and its human ortholog NGAL sequester iron-containing siderophore as an innate immune mechanism to limit the growth of bacteria, especially during infection or inflammation." (PMID 27254317, 2016). "Taken together, these results indicate that c-di-GMP would participate in resistance to host defense by interfering with the innate immune protein LCN2 to ensure bacterial survival during infection." (PMID 26390966, 2015). "QRT-PCR confirmed significant induction of RegIIIβ, RegIIIγ, Lcn2, Ltf, S100a8, and S100a9 mRNA levels following infection." (PMID 26658437, 2015). "In CSF, bacteria were detected at 2 h of infection and lipocalin 2 was detected at 5 h of infection in mice that received the highest bacterial dose and at 24 h for both doses of infection." (PMID 24885531, 2014). "Lipocalin 2 knock-out mice succumbed rapidly after intraperitoneal infection of Escherichia coli, in contrast to wild-type mice." (PMID 24885531, 2014). "Up-regulated gene expression of four AMPs (Chi3l1, Cxcl17, Lcn2, Spli) was found in the lungs during the whole course of infection." (PMID 25137043, 2014). "Metal limitation in the host is further enhanced during infection by the secretion of antimicrobial proteins that sequester metal ions, such as lipocalin-2 and calprotectin." (PMID 24478990, 2014). "Lipocalin-2 is one of the most abundant antimicrobial proteins released by epithelial cells and neutrophils during infections in the gut and respiratory mucosa with pathogens like S. Typhimurium and K. pneumoniae, respectively." (PMID 24478990, 2014). "Lipocalin 2 is an adipokine, whose secretion is highly regulated by activation of inflammation and infection, whereas lipopolysaccharide (LPS) and TNFα are two strong inducers of LCN2 production." (PMID 23285167, 2012). "The lungs were removed 48 hours post-infection and examined for lipocalin 2 and MMP9 (a myeloid marker protein) by immunohistochemical staining and western blotting." (PMID 20633248, 2010). "We first examined the effect of a short-term infection (48 hours) of a lipocalin 2 knock-out mouse compared to wild-type littermates." (PMID 20633248, 2010).
infection (continued). "Both of these bacterial strains readily infect mice in an intranasal inoculation model despite a strong up-regulation of lipocalin 2 in the nasal epithelium in response to the infection." (PMID 20633248, 2010). "Strong immunostaining for lipocalin 2 is seen in bronchial epithelial cells and in type II pneumocytes of the alveoli following infection with E. coli." (PMID 20633248, 2010). "Significant higher bacterial numbers were observed in the lungs of lipocalin 2 knock-out mice on days 2 and 5 after infection with E. coli (p < 0.05)." (PMID 20633248, 2010). "It has been demonstrated previously that lipocalin 2 is protective against infection by E. coli injected directly into the peritoneum." (PMID 20633248, 2010). "Induction of innate immune responses during infection can modulate iron homeostasis pathways through induction of hepcidin (Hamp1) and Lcn2." (PMID 20184753, 2010). "Migration of myeloid cells to the site of infection also contributed to an increased lipocalin 2 level in the lungs." (PMID 20633248, 2010). "In addition to its role in fighting infection, LCN2 is involved in various physiological processes, such as inflammation, immune response, and iron metabolism." (PMID 40502700, 2025). "Moreover, our bioinformatics analysis identified LCN2 as one of the hub genes in infection and neurological inflammation." (PMID 40025014, 2025). "Pathogen‐induced infection may trigger the LCN2 signaling pathway, including an increase in LCN2 expression, subsequently leading to apoptosis, oxidative stress, and site‐specific inflammation promoting tumorigenesis." (PMID 39511728, 2025). "Upon infection with C. rodentium, AhrdCAIR/dCAIR mice cleared the bacteria faster than wildtype mice, made more IL-22 and exhibited lower inflammation indicated by fecal Lipocalin-2 (Lcn2) expression." (PMID 40502009, 2025). "Lipocalin 2, also known as neutrophil gelatinase-associated lipocalin (NGAL), is considered a biomarker of diseases, including inflammation, tumors, infection, and kidney injury, is detectable in urine, blood, and stool, and has been proposed as a biomarker of active UC." (PMID 40077417, 2025). "While the host defends against infection by producing lipocalin-2 to sequester enterobactin, increased citrate may serve as an alternative iron source, bypassing siderophore reliance." (PMID 40565144, 2025). "However, in response to injury, infection, or other inflammatory stimuli, LCN2 expression is rapidly elevated." (PMID 40375133, 2025). "In order to assess the presence of any baseline inflammation, which may be induced by the diet shift, we measured pre-infection fecal lipocalin-2 (LCN-2) concentration, which is a marker of low-grade inflammation." (PMID 38745106, 2024). "However, in organs like the brain, heart, skeletal muscle and spleen, Lcn-2 is only expressed under pathological states, such as infection, inflammation and cancer." (PMID 38533497, 2024). "In the PPI network, the central genes of cluster 1 between normal + infection group and undernutrition 75% + infection group were Mpo (0.31 fold change), Lcn2 (0.38 fold change) and Ltf (0.28 fold change), which were downregulated in undernutrition 75% + infection group." (PMID 38185681, 2024). "Our results revealed that Lcn2 may regulate gut microbiota and metabolome components, changing the intestinal environment, thereby affecting the infection status of M. bovis." (PMID 39051782, 2024). "In both experimental groups, infection induced an equal increase of fecal Lcn-2 levels." (PMID 39366940, 2024). "Like Lcn2, lactoferrin is released by neutrophils at sites of infection." (PMID 36857468, 2023). "LCN2 secretion is induced by infection, injury, and metabolic disorders." (PMID 37240031, 2023). "This study provides evidence for a role of LCN2 in neonatal infection/inflammation." (PMID 37496672, 2023).
infection (continued). "Moreover, LCN2 can stop the proliferation of M. tuberculosis in vitro and cultured cell lines of macrophages, suggesting its role in iron regulation in infection." (PMID 37942316, 2023). "Interestingly, the infection-related increase of LCN2 was diminished in mice that displayed additional Nlrp3 or Gsdmd deficiency." (PMID 37240031, 2023). "In summary, ELANE and LCN2 were enriched in neutrophil activation and correlated with infection and septic shock, especially ELANE as the only prognostic gene could participate through NETs formation and pyroptosis pathways." (PMID 36911395, 2023). "During infection, neutrophils, macrophages, epithelial cells, and other cells produce LCN2." (PMID 37932342, 2023). "Ferrichrome cannot be bound by the siderophore-binding host protein lipocalin-2, so it may be a valuable source of iron during infection." (PMID 36946760, 2023). "Lcn2 is an acute phase protein that can sequester intracellular iron bound to catecholate siderophores, and is more likely to transport iron to tissues during infection." (PMID 36066082, 2022). "Collectively, these findings support the hypothesis that the robust expression of LCN2 during infection may be a countermeasure employed by the host to restrict bacterial survival, proliferation, or dissemination by inhibiting iron acquisition by A. baumannii." (PMID 36054235, 2022). "A previous study that introduced E. coli HB-101 into lung-infection-model mice in an immunosuppressed state following suppression of Lipocalin 2 (an effector molecule of the innate immune system) reported infection from the lung to other organs at 48 h after infection." (PMID 35269610, 2022). "It is believed that LCN2 also prevents massive systemic inflammation by functioning as an anti-inflammatory agent to induce hypoferremia of infection, reduce free iron availability, and thus limit oxidative damage caused by the generation of ROS through Fenton chemistry." (PMID 36054235, 2022). "LCN-2 is a key mediator of the initial neutrophil response to the infection." (PMID 35265399, 2022). "Lipocalin 2 (LCN2), a glycoprotein expressed in adipose tissue and the liver, participates in innate immune system reaction, being critical in the acute phase response to infection." (PMID 34835964, 2021). "This may be one of the reasons for the increase of LCN2 expression in early infection, which depends on the activation of the NF-kB pathway." (PMID 34616693, 2021). "Then, to examine whether the expression of LCN2 in liver tissues is upregulated during infection, we evaluated the protein level of LCN2, which was performed in infected tissue samples and normal tissue samples from mice with S. japonicum." (PMID 34616693, 2021). "On the other hand, NGAL/LCN2 is required to limit infection." (PMID 33510370, 2021). "Our study highlights the essential role of NF-κB/LCN2 in early innate immune response to infection." (PMID 34616693, 2021). "Profiling protein levels in plasma of MR‐ProADM and lipocalin 2 could contribute to stratification of the severity of infection, particularly in settings where calculation of the SOFA score is not feasible." (PMID 32073224, 2020). "LCN2 is released by various cell types and is a biomarker of inflammation and infection." (PMID 31270736, 2020). "Lipocalin 2 (LCN2) regulates infection response and increases in liver injury." (PMID 32968110, 2020). "Similar to the reduced levels of IL-8, levels of pro-inflammatory cytokines IL-1α,−1β,−4, and−6 as well as LCN2 were also reduced upon P4 ΔentA infection in mammary gland homogenates of both mouse strains compared with their P4-infected counterparts (P ≤ 0.08)." (PMID 33240956, 2020). "In addition, lipocalin-2 concentrations were similar in colons of both Fut2+/+ and Fut2-/- mice after infection with S. Typhimurium ΔaroA ΔstdA." (PMID 31329635, 2019).